IL17A (interleukin 17A)
Diseases named in the same sentence as IL17A in open-access papers (continued):
Sharing a sentence is not in itself a finding about the gene and the disease.
renal fibrosis (39 papers, 2014 to 2026). A final common manifestation of a wide variety of chronic kidney diseases characterized by glomerulosclerosis and tubulointerstitial fibrosis. "Conversely, inhibiting IL-17A using tamibarotene (commonly known as Am80) or neutralizing IL-17A with recombinant IL-17RC effectively mitigates post-AKI renal fibrosis." (PMID 40521043, 2025). "Anti-IL-17A or anti-IL-17 receptor A subunit monoclonal antibodies significantly reduced TGF-β levels in TGF-β-mediated renal fibrosis." (PMID 40028265, 2025). "Studies on renal fibrosis following AKI in mouse models have revealed that IL-17A promotes the chemotactic aggregation of neutrophils and fibroblasts, thereby exacerbating renal fibrosis." (PMID 40521043, 2025). "ILC3s were enriched in the fibrotic niche in human and mouse kidneys and produced IL‐17A to promote renal fibrosis in a PD‐1‐dependent manner." (PMID 40801800, 2025). "Intestinal ILC3s migrate to the kidney through CXCL16/CXCR6 axis and IL‐17A derived from ILC3s in PD‐1‐dependent manner promotes renal fibrosis." (PMID 40801800, 2025). "Collectively, these results suggested that the combined treatment of anti-VEGF-B and anti-IL-17A alleviated renal fibrosis in db/db mice." (PMID 36646672, 2023). "Masson staining, immunohistochemical staining of fibronectin and α-SMA were conducted to determine the efficacy of anti-VEGF-B or/and anti-IL-17A on renal fibrosis." (PMID 36646672, 2023). "We therefore administered IL-17A antibody twice weekly by intraperitoneal injection after ischemic insults and found that TLOs formation was abolished and renal fibrosis was attenuated." (PMID 33391465, 2021). "Together with the evidence that Il17a-/- aged mice had smaller TLOs after renal ischemia reperfusion injury, the administration of blocking antibodies to IL-17A also reduced the development of TLOs correlating with a modest reduction in renal fibrosis." (PMID 33391465, 2021). "For example, in a model of obstructive nephropathy, the C3 component produced locally by macrophages promoted renal fibrosis through increasing T-cell proliferation and IL-17A expression." (PMID 34540858, 2021). "In renal obstruction models, IL-17A, a major member of the IL-17 cytokine family, facilitated renal fibrosis by RANTES-mediated leukocyte infiltration." (PMID 34616308, 2021). "Moreover, IL-17A has been confirmed to be relevant to infections, autoinflammatory diseases, and renal fibrosis (Kolls and Lindén, 2004; Peroumal and Biswas, 2023)." (PMID 40093533, 2025). "In obstructive uropathy models, IL-17A promotes renal fibrosis by increasing TGF-β1 expression." (PMID 40977724, 2025). "As expected, the results confirmed that simultaneous blockade of VEGF-B and IL-17A could ameliorate renal dysfunction by decreasing renal lipid accumulation and inflammatory response, they also alleviated the renal fibrosis in vivo." (PMID 36646672, 2023). "Nevertheless, some other studies raised doubts due to blockade or deficiency of IL-17A having no beneficial effect on preventing renal fibrosis progression following severe IRI." (PMID 34616308, 2021). "We found that IRI-induced TLOs were smaller in Il17a-/- mice, and renal fibrosis was alleviated." (PMID 33391465, 2021). "In addition, IL-17A regulates renal fibrosis, further influencing BP." (PMID 40028265, 2025). "Therefore, it was necessary to examine whether simultaneous inhibition of VEGF-B and IL-17A could alleviate renal fibrosis in db/db mice." (PMID 36646672, 2023). "Gamma delta T cells are one of the sources of IL-17A that is increased in cisplatin-induced AKI and UUO-induced renal fibrosis." (PMID 34616308, 2021). "Importantly, the combined administration of anti-IL-17A and anti-VEGF-B antibodies remarkably reversed the genes which are closely related to lipid metabolism, inflammation, and renal fibrosis." (PMID 36646672, 2023).
renal fibrosis (continued). "We found that eliminating both VEGF-B and IL-17A significantly ameliorated renal dysfunction and disease progression in DKD mice by reducing the ectopic lipid deposition, and inflammation and inhibiting the renal fibrosis response." (PMID 36646672, 2023). "In addition, IL-17A neutralization treatment did not ameliorate AngII-induced renal fibrosis." (PMID 31572188, 2019).
Cerebral ischemia (38 papers, 2011 to 2025). Restriction of arterial blood supply to the brain associated with insufficient oxygenation to support the metabolic requirements of the tissue. "For instance, studies from have shown that IL-17A knockout (IL17A−/−) exhibited a significant reduction in infarct volume after cerebral ischemia/reperfusion (I/R) injury." (PMID 40276600, 2025). "SphK1 was induced in microglia after cerebral ischemia, and the knockdown of SphK1 decreased IL17A production after oxygen/glucose deprivation." (PMID 37239854, 2023). "The current research examined the neuroprotective effects of EE on angiogenesis in an astrocytic interleukin-17A (IL-17A)-dependent manner following cerebral ischemia/reperfusion (I/R) injury." (PMID 36873773, 2023). "A large amount of ROS is produced during cerebral ischemia and reperfusion, and mass spectrometry demonstrates that IL-17A correlates with oxidative stress." (PMID 28912678, 2017). "It should moreover be noted that the pro-angiogenetic effect of IL-17A may be dependent on the IL-6/STAT3 signaling pathways under EE conditions after cerebral ischemia; this matter should be further explored in the future." (PMID 36873773, 2023). "However, IL-17A is mainly produced by astrocytes in the delayed phase and promotes neurogenesis, synaptogenesis, and functional recovery after cerebral ischemia." (PMID 36873773, 2023). "While we found no increase in the number of IL-17A+ mast cells in patients with low tpO2 levels, previous studies suggest mast cells respond early to hypoxic insult in rat models of cerebral ischemia." (PMID 21887369, 2011).
preeclampsia (38 papers, 2015 to 2025). Preeclampsia is a hypertensive disorder of pregnancy that is characterized by new-onset hypertension with proteinuria presenting after 20 weeks of gestation, and depending on mild or severe forms may initially present with severe headache, visual disturbances, and hyperreflexia. "Interleukin 17A has been implicated in the pathophysiology of both human immune deficiency virus and preeclampsia." (PMID 32550763, 2020). "The mean serum levels of IL-17A in pregnant women with preeclampsia and healthy pregnant women were 2.79±1.26 and 2.86±1.69, respectively." (PMID 31897391, 2019). "For example, in a preeclampsia model, IL-17A neutralization blunted NK cell cytotoxicity." (PMID 39504049, 2024). "Our findings suggested that IL-17A play a role in the pathophysiology of preeclampsia and that in the presence of HIV infection, chronic HAART exposure is associated with increased levels of IL-17A which might be associated with the pathophysiology of EOPE." (PMID 32550763, 2020). "Additionally, since serum levels of IL-17A cytokines were tested from peripheral circulating blood rather than fetomaternal interface, future studies should be done on serum from the fetomaternal interface since the primary source of the pathogenesis of preeclampsia arises from the placenta." (PMID 32550763, 2020). "Our results (higher percentage of CD4+IL-17+) are consistent with reports of increased CD4+IL-17A+ cells in blood and increased RORc mRNA expression in the decidua and PBMCs in women with gestational hypertension, including preeclampsia." (PMID 41156157, 2025). "Therefore, the aim of our study was to assess the population of Treg (CD4+CD25+FoxP3+) and Th17 lymphocytes, as well as the intracellular expression of IL-17A, IL-17F, IL-21, and IL-22 in women with PIH (including preeclampsia)." (PMID 41156157, 2025).
skin infection (38 papers, 2012 to 2025). An inflammatory process affecting the skin, caused by bacteria, viruses, parasites, or fungi. "IL-17A and to a lesser degree, IL-22 have been linked to protection in mouse models of skin infection yet IL-26 remains quite understudied, likely due to its absence in the mouse genome and to the difficulty to reveal it by intracellular cytokine staining." (PMID 39981298, 2024). "Patients and mice with defects in IL-17A, IL-17A receptor chains, or IL-17A signaling, or defects in neutrophil number or function, are susceptible to mucosal and skin infections caused by S. aureus." (PMID 34747366, 2021). "Mice deficient in IL-17A or IL-17F have proved prone to skin infections caused by gram-positive bacteria such as S. aureus." (PMID 29590259, 2018). "IL-17A production by skin TCRγδ+ cells in response to IL-1 and IL-23 produced by epithelial and immune cells is important for restraining S. aureus skin infection." (PMID 34747366, 2021). "In a different study, vaccination with a multiple antigen presenting system with six staphylococcal proteins led to the differentiation of CD4+ T cells that produced both IFNγ and IL-17A, which mediated protection against both bloodstream and skin infections." (PMID 33291260, 2020). "During skin infection, IL-17A and IL-22 produced by activated T cells induce keratinocytes to express antimicrobial factors CXCL8 and β-defensin 2 and 3 (BD-2 and -3), which critically control S. aureus infection." (PMID 33271763, 2020). "Like intradermal and subcutaneous infection with S. aureus, superficial S. aureus skin infection elicited a TCRγδ+ cell–dependent protective local IL-17A response that promoted neutrophil recruitment and AMP production, both of which are important for the clearance of S. aureus." (PMID 34747366, 2021). "To investigate whether IL-17A restrains superficial skin infection by S. aureus, we examined Il17a–/– mice." (PMID 34747366, 2021). "Indeed, this notion is supported by the fact that γδ T cell derived IL-17A is necessary for defense against S. aureus skin infection." (PMID 23861974, 2013). "In a Staphylococcus aureus skin infection model, IL-17A/F−/− mice had reduced IL-1α, IL-1β, and TNF-α,39 suggesting that IL-17 regulates these proinflammatory mediators." (PMID 39504049, 2024). "IL-17A has long been reported to have an important role in cutaneous and mucosal host defense to control the microbiota and was found to be involved in defense against MRSA skin infection in mice." (PMID 39208402, 2024). "Although IL-17A did not improve survival outcomes during bacteremia in our model, IL-17A limits the systemic dissemination of S. aureus from skin infection to kidneys." (PMID 37483624, 2023). "IL-17A, IL-1α, and IL-1β are believed to be protective during mouse MRSA skin infections." (PMID 33573328, 2021). "Mice that produce neither IL-17A nor IL-17F are susceptible to skin infection by S. aureus, since TH17-type cytokines IL-17A and IL-17F critically recruit neutrophils to clear S. aureus." (PMID 33271763, 2020).
lung adenocarcinoma (37 papers, 2013 to 2026). A carcinoma that arises from the lung and is characterized by the presence of malignant glandular epithelial cells. "In this study, we studied the effect of IL-17A on the biological behavior of lung adenocarcinoma cell lines of A549 and H1299 in vitro." (PMID 36349316, 2022). "Intranasal treatment with a neutralizing anti-IL-17A antibody in a lung adenocarcinoma model was also shown to reduce tumor growth." (PMID 32203101, 2020). "The combined classifier of IL-6 and IL-17A was ranked as the best model (AIC=269) to predict survival outcome of stage I lung adenocarcinoma patients." (PMID 28402963, 2017). "In summary, Th17 cells from lung adenocarcinoma patients, compared with the control groups, expressed high levels of IL-17A." (PMID 26582240, 2015). "Therefore, the aim of the present study was to investigate the effects of IL-17A on A549 and H1299 lung adenocarcinoma cells in vitro and to determine whether NLRP3 is involved in the IL-17A-mediated effects." (PMID 36349316, 2022). "Moreover, the Th17 cells from lung adenocarcinoma patients produced the highest levels of IL-17A." (PMID 26582240, 2015). "IL-17A was highly expressed in NSCLC cells, and to further understand its effect on tumor cells, we chose lung adenocarcinoma cell lines A549 and SPC-A-1 to construct IL-17A knockdown, over-expressed and normal control cells with lentivirus." (PMID 37978543, 2023). "The results showed that ACAN, CDKN3, GRIN2A, IL17A, KCNQ2, TIMP1, and UCHL1 were significantly up-regulated in lung adenocarcinoma cells." (PMID 36147496, 2022). "Accordingly, IL-17A and VEGF serum levels in patients with lung adenocarcinoma were positively correlated, and in tumoral cell lines, IL-17A induced VEGFA expression." (PMID 32987705, 2020). "The combined prognostic role of IL-6, CRP plus IL-17A in stage I lung adenocarcinoma has not been reported previously." (PMID 28402963, 2017). "Interestingly, in lung adenocarcinoma patients, percentages of ROR-γt+ CD4+ T-cells were higher compared to the percentages of IL-17A-producing CD4+ T-cells." (PMID 26582240, 2015). "In the analysis of the TCGA dataset, we found that the expression of IL17A was significantly positively correlated with the expression of CD8A in invasive breast carcinoma (BRCA), liver hepatocellular carcinoma (LIHC), and ovarian serous cystadenocarcinoma (OV) in lung adenocarcinoma in TCGA." (PMID 35459193, 2022). "In lung adenocarcinoma patients, significant increases were found in the MFI values of IL-17A compared with the nonsmoking group (data not shown)." (PMID 26582240, 2015).
nasal polyps (37 papers, 2009 to 2025). "The level of mRNA encoding IL-17A was significantly higher in the nasal polyp groups than in controls." (PMID 35075349, 2022). "The CRSwNP group showed significantly elevated MPO activity, PI3K, p-AKT protein, HIF-1α, and IL-17A mRNA levels in nasal polyps." (PMID 35075349, 2022). "We found that the level of IL-17A mRNA was significantly higher in nasal polyp groups than in controls." (PMID 35075349, 2022). "Based on previous studies related to the inflammatory microenvironment of nasal polyp tissues, seven factors, IL-5, IL-8, IL-17A, IL-17E, IL-18, IL-27 and IFN-γ, were selected for analysis." (PMID 33737534, 2021). "Staphylococcus aureus enterotoxin B stimulation of dispersed nasal polyp cells induced significant interleukin 17A (IL-17A) synthesis." (PMID 30778348, 2019). "Acute sensitivity to SEB would perpetuate the persistent inflammation seen in nasal polyps, but also in normal epithelium, where IL-17A expression can activate pathways resulting in the recruitment of neutrophils." (PMID 29843476, 2018). "Outside the context of mTSS, SEB has been shown to induce inflammatory activation in nasal epithelial cells resulting in IL-17A expression, with particularly high levels of this cytokine being found in nasal polyps." (PMID 29843476, 2018). "Current evidences indicate that IL-17A is highly expressed in chronic rhinosinusitis with nasal polyps (CRSwNP)." (PMID 30283454, 2018). "When divided the nasal polyps into IL-17Ahigh and IL-17low subgroup, we found the mRNA levels of IL-17A, MUC5AC and act1 were significantly higher in IL-17Ahigh polyp tissues than those in IL-17Alow polyp tissues (p<0.05)." (PMID 24892823, 2014). "Because IL-17A has been proposed to be significantly upregulated in nasal polyps, we firstly examined the expression of IL-17A and MUC5AC, as well as goblet cell hyperplasia, in polyp tissues and normal controls." (PMID 24892823, 2014). "In Asian patients with CRS, the expression of IL-22 is associated with IL-17A and TNFα and the absence of nasal polyps." (PMID 35455762, 2022). "Several studies showed that IL-17A was significantly increased in nasal polyps (NPs)." (PMID 34222494, 2021). "Combined stimulation with IL-17A and TNF-α induced further upregulation of MIP-3α/CCL20 expression in the nasal polyp fibroblasts." (PMID 23283206, 2009). "IL-17A and TNF-α synergistically induced MIP-3α/CCL20 production by nasal polyp fibroblasts in a dose- and time-dependent manner." (PMID 23283206, 2009). "Polycytidylic acid (poly (IC)) is the ligand for TLR3, and exposure to poly (IC) selectively induces IL-10, but not IL-5, IL-13, IFN-γ or IL-17A, production by nasal polyp cells." (PMID 36003393, 2022). "The results showed that the expression of IL-17A was upregulated in nasal tissues of patients with CRSwNP compared to those with chronic rhinosinusitis without nasal polyps (CRSsNP) and controls." (PMID 30283454, 2018). "The number of IL-17A positive cells were greater in nasal polyps of atopic patients than non-atopic (p = 0.0128, RR = 0.33, 95% CI: 0.1497 to 0.7421)." (PMID 24141678, 2013). "The numbers of IL-17A positive cells were greater in nasal polyps of atopic patients than nonatopic (p = 0.0128)." (PMID 24141678, 2013). "Our results suggest that IL-17A and IL-17F, but not IL-17E, contribute to infiltration of Th17 cells and DCs into upper airway inflammatory sites such as nasal polyps through the production of MIP-3α/CCL20 by fibroblasts." (PMID 23283206, 2009). "It is interesting to speculate whether IL-17A, which is released from Th17 cells, is capable of inducing MIP-3α/CCL20 production in nasal polyp fibroblasts synergistically with TNF-α, which is abundant in nasal polyps." (PMID 23283206, 2009). "However, in the present study, we have demonstrated that IL-17A and TNF-α synergistically induced MIP-3α/CCL20 in nasal polyp fibroblasts." (PMID 23283206, 2009).
nasal polyps (continued). "Here we sought to quantify IL-17A, IL-17F, IL-21, and IL-22 cytokines produced by Th17 cells in mucosal tissue and peripheral blood of CRSwNP, CRS without nasal polyps (CRSsNP) and control patients." (PMID 29311948, 2017). "Combined stimulation with TNF-α plus IL-17A or IL-17F, but not IL-17E, synergistically induced release of MIP-3α/CCL20 by the nasal polyp fibroblasts." (PMID 23283206, 2009).